NOTCH1 (notch receptor 1)
Diseases named in the same sentence as NOTCH1 in open-access papers (continued):
Sharing a sentence is not in itself a finding about the gene and the disease.
cancer (continued). "The functional interchangeability of mammalian Notch receptors (Notch1-4) in normal and pathophysiologic contexts such as cancer is unsettled." (PMID 22022427, 2011). "DLL4-mediated NOTCH1 signaling represents an essential pathway for vascular development and has emerged as an attractive target for angiogenesis-based cancer therapies." (PMID 21824400, 2011). "Notch1 signaling is increased in a variety of cancers and activates downstream target genes, including HES1, HES5, DTX1, NRARP, and c-MYC." (PMID 20161710, 2010). "As such, our findings indicate that the same regulatory mechanisms that trigger the final stages of the terminal differentiation process can also promote cancer development by suppressing the intermediate commitment stages (for which Notch1 is required)." (PMID 20442780, 2010). "The relative binding affinities of NRR and LBD antibodies for Notch1 varied among cancer cell lines." (PMID 20161710, 2010). "It regulates invasion, metastasis, EMT and angiogenesis in various carcinomas, regulating features similar to Notch1." (PMID 19953094, 2010). "Our data re-iterates the role of Notch1 in carcinoma progression and places RhoC as its downstream target." (PMID 19953094, 2010). "There are surmounting evidences elucidating the contribution of two such pathways including Notch1 and RhoC to carcinoma progression." (PMID 19953094, 2010). "While Notch1 showed a predominantly low expression (1+ or 2+) in normal tissues, in cancers it was expressed at 3+ levels." (PMID 20030805, 2009). "We detected Notch1 expression in both normal and cancerous breast tissue, with cancer samples showing a higher level of expression." (PMID 20030805, 2009). "Thus, providing the best evidence that gefitinib-acquired resistance in cancer cells of the lung undergoing EMT occurs through Notch-1 signalling activation." (PMID 41321380, 2025). "This suggests that modulation of b-1,4-GalT-V could serve as a potential therapeutic strategy in targeting Notch-1-related signaling pathways in cancer treatment." (PMID 40869407, 2025). "The PTMs, deleterious SNPs, IDRs, and PTMs in the IDR regions, as critical regulators of cancer cells present in NOTCH1, may be involved in processes by which cancer cells revamp and lead to tumorigenesis." (PMID 41451346, 2025). "Notably, although Notch1 signaling has emerged as a prominent regulator of EMT in various cancers and fibrotic diseases, its role in mediating EMT within Barrett’s esophagus has not been clearly established, representing a significant gap in current research." (PMID 40629071, 2025). "Role of circRNAs in the regulation of NOTCH 1 expression in cancers." (PMID 40761890, 2025). "The distribution of reads obtained via ChIP-Seq was strongly associated with the Hippo and Notch signaling pathways in cancer cells or tumors, whereas the PI3K-AKT signaling pathway in primary human TH1 cells were shown as the robust tracks of the YAP1, Notch1 or AKT1 gene promoter region." (PMID 40430053, 2025). "Thus, β-1,4-GalT-V enhances Notch-1 stability and function through galactosylation, linking it to cancer progression, immune regulation, and angiogenesis." (PMID 40869407, 2025). "Importantly, our findings revealed that AP2M1 exerts a significant influence on the expression levels of NOTCH1, a key regulatory gene in hematopoiesis and cancer development." (PMID 41082341, 2025).
cancer (continued). "growth‐proliferation cell cycle‐associated genes such as Myc and Notch1,110 cancer‐associated genes such as Cdkn2a and Alpl, absence of TCR genes such as Trac and Trbc1/2 and elevated RPG expression, a distinct subset of precancerous T cells emerged." (PMID 40887856, 2025). "NOTCH1 in stage IV cancers was more upregulated (4.03±0.48) than in stage III (3.26±0.56; p<0.001)." (PMID 40672020, 2025). "This further indicates how β-1,4-GalT-V could potentially be a focal tool in learning more about cancers that have abnormal Notch-1 activity as well as offering a potential clinical strategy." (PMID 40869407, 2025). "Notch1 ablation enhances cancer cell responsiveness to PD-1/PD-L1 blockade." (PMID 40977688, 2025). "NOTCH1 inhibition was demonstrated to reduce cancer stem-like cells and cancer self-renewal abilities in vitro and in vivo studies looking at HNSCC cell lines and, thus, provide a promising target for HNSCC management though once again, most of this research remains in the early pre-clinical phase." (PMID 40868227, 2025). "Interestingly, the combined activity of both pathways (NOTCH1 and MAPK) was associated with poorer cancer-specific and overall survival, acting as an autonomous prognostic factor." (PMID 41008920, 2025). "Notch1 also plays a critical role in maintaining cancer cell stemness." (PMID 40182121, 2025). "In line with their integration in promoting cancer, our results further demonstrate that MUC1-C and NEAT1 regulate common sets of genes associated with chronic inflammation, induction of EMT and activation of the NOTCH1/2 stemness factors." (PMID 38802648, 2024). "While CAFs-S1 stimulate cancer cell migration and initiate an EMT through CXCL12 and TGFB pathways, highly contractile CAFs-S4 induce cancer cell invasion in 3 dimensions via NOTCH signaling (NOTCH1, bSE = 3.0; NOTCH2, bSE = 2.6; NOTCH3, bSE = 1.4; NOTCH4, SE = 3.0)." (PMID 39335478, 2024). "Taken together, we conclude that targeting NOTCH1 signaling could be an attractive therapeutic strategy against cancer over the next decade." (PMID 38532427, 2024). "Moreover, the downregulation of Notch-1, introduced by siRNA transfection, inhibited cancer-cell survival, migration ability, and HUVEC tube formations." (PMID 38474604, 2024). "We further addressed this point of recurrent mutations in cancer by conducting a global survey of recurrent mutational sites in the COSMIC dataset, which revealed that the site in NOTCH1 pG4 ranked fifth, marking it as a likely prominent mutational hotspot in cancer." (PMID 39341500, 2024). "The mutations in Notch1 result in the aberrant transcriptional activation of its downstream genes (MYC, HES1, HEY, CCND1, etc.)involved in anabolic pathways and thus drive the neoplastic progression of several types of cancers." (PMID 39456548, 2024). "Aim of the study is to investigate how targeting hCAF/iCCA cross-talk with a Notch1 inhibitor, namely Crenigacestat, may affect cancer progression." (PMID 39415286, 2024). "Altogether, it was concluded that MBZ suppresses cancer progression through inhibition of the Notch1 signaling pathway, and Notch1 could be a critical target in T-ALL." (PMID 39456548, 2024). "In summarizing our study, CD133 was exclusively expressed in cancer cells compared to stromal and immune cells and was associated with other CSC markers (CD24, NOTCH1, DLL1, and ALDH1A1), as well as enriched WNT/β-Catenin, Hedgehog, and NOTCH signaling, validating CD133 as a CSC marker." (PMID 38585981, 2024). "Notch1 inhibition via either γ-secretase inhibitor, short interference RNA, or monoclonal antibodies offers a great approach alone or in combination with other therapeutic agents to combat cancer." (PMID 39456548, 2024).
cancer (continued). "Previous work from our group and Dr. Stegmaier’s laboratory identified the Sarco-endoplasmic Ca2+-ATPase (SERCA) as a potential therapeutic target in NOTCH1-mutated cancers, overcoming the innate limitations associated with GSI that equally target WT and mutated NOTCH1 proteins." (PMID 38255842, 2024). "There is currently no specific treatment available for cancers caused by NOTCH1 PEST domain mutations." (PMID 38255842, 2024). "In PNETs, the expression of Notch1 signaling was highly related to cancer progression." (PMID 38279330, 2024). "A significant increase in the frequency of somatic copy number alterations was observed in the known cancer drivers NOTCH1, PPP6C, RAC1, EIF4G1, and PIK3CA in the transition from potentially premalignant (oral) lesions to HNSCC, which was correlated with their expression." (PMID 39613893, 2024). "However, continued investigation is needed to validate these potential targets and the possible impact of drugs or agents on NOTCH1-dependent cancers." (PMID 38043798, 2024). "Moreover, Doxo led to a significant increase in the expression of Notch1 signaling genes, and according to previous studies, Doxo can strongly increase the expression of Notch1 pathway components in cancer cells." (PMID 38291201, 2024). "Hence, the nuclear interactome of Notch1 generated in this study will benefit further investigations of the molecular mechanisms of NOTCH1 functions and regulation that govern Notch transcriptional activity in normal and cancer cells." (PMID 38043798, 2024). "Not surprisingly, the disease most associated with NOTCH1 core-proximal proteins was predicted to be cancer." (PMID 38043798, 2024). "Furthermore, cancers in which Notch1 is overexpressed display increased likelihood of lymph node metastasis, higher TNM staging, and significantly reduced overall patient survival rates." (PMID 38866828, 2024). "Why does the role of Notch1 vary in different cancer cells, even within the same cancer type?" (PMID 40034926, 2024). "Our data suggest that HDAC1 and some other identified interacting proteins such as GATAD2B in this study may be essential partners for NOTCH1 function and may serve as important therapeutic targets in NOTCH1-dependent cancers." (PMID 38043798, 2024). "Further analysis of the Cancer Cell Line Encyclopedia (CCLE) database showed that both NOTCH1 and USP11 were found to be collectively highly expressed in T-ALL cell lines compared with cell lines from other cancer types, and their levels present with a positive correlation in the T-ALL group." (PMID 38007584, 2024). "Comparison of transcriptomic changes between MOC2 control and EphB4 knockout cell lines showed higher expression of TGF beta receptors 1 and 2, NOTCH1, and FOXC1, a transcription factor implicated in cancer cell plasticity, treatment resistance, invasion, and epithelial-mesenchymal transition (EMT)." (PMID 39091728, 2024). "Therefore, ASPH SMIs can reduce Notch1 signaling and alter the characteristics of cancer cells 27,28." (PMID 38817852, 2024). "Notch-1 knockdown caused the promotion of cell apoptosis and reversed EMT in cancer cells." (PMID 38474604, 2024). "We also provided one proof-of-principle example for the first time in this study that GATAD2D and NOTCH1 may directly interact in NOTCH1-mutated MOLT-4 and MB157 cancer cells." (PMID 38043798, 2024). "Furthermore, the mean percentage of NOTCH1-positive expression in malignant tumors was comparable to that of normal cases (p = 0.168), and precancerous and benign tumors (p = 0.0.785 and p = 0.615, respectively)." (PMID 39063983, 2024). "Indeed, it has been shown that targeting Notch1 enhances the efficacy of ERK1 inhibitors in cancer patients." (PMID 38272919, 2024). "Strong membranous Notch1 expression was often observed at the border of cancer nests at late point." (PMID 38585261, 2024).
cancer (continued). "Although there were some confounding variables between the subjects, including the treatment status of HER2-targeted or hormonal therapy, cancer patients with hyperglycemic episodes had significantly higher NOTCH activity based on immunofluorescence staining of nuclear NOTCH1." (PMID 36707514, 2023). "In addition, dysregulated Notch1 signaling has been found in numerous cancers, including hematological malignancies." (PMID 36768603, 2023). "The NOTCH1 mutation frequency is significantly higher in cancers that are negative for human papillomaviruses (HPV), indicating a different etiology of these distinct cancer subtypes." (PMID 37760535, 2023). "Therefore, our current study provides insights into m6A modulation on cancer cell plasticity and Notch1 signaling overactivation and potential therapeutic targets for metastatic LUAD." (PMID 37171793, 2023). "Its anti-cancer properties are based on antioxidant activity (lowering the concentration of ROS, catalase, and glutathione peroxidase) and anti-inflammatory activity related to the influence on the transcription factor NFkappaβ and Notch-1." (PMID 37570691, 2023). "This work identified Notch1 signaling as a major regulator of cancer-induced WAT remodeling." (PMID 37749321, 2023). "Hence, Notch1 is an attractive target for eradicating BCSCs, and several preclinical studies have confirmed its potential role as a therapeutic target in cancer treatment." (PMID 36909163, 2023). "Notably, MYB, KIT, and FABP7 (the top-ranked signature genes) directly interact with NOTCH1, and these interactions have been reported to be involved in regulating cancer stem cell differentiation." (PMID 36879115, 2023). "We then explored by real-time qPCR the impact of miR-662 overexpression in MDA-MB-231 cells on expression levels of well-established stemness markers that are involved in embryogenesis and cancer –NOTCH1, WNT7b, ZEB1, TCF3, CTNNB1, CD44, CD24, SNAI2, OCT-04, c-MYC, EZH2–." (PMID 37443350, 2023). "Therefore, with its potent activity and lack of apparent toxicity, ASR490 provides the necessary selectivity and therapeutic window for cancer therapeutics targeting the Notch1 pathway and selectively inhibiting BCSC populations within tumors." (PMID 36909163, 2023). "The detected cancer genes NOTCH1 and RUNX1 could possibly influence the RUNX3 signaling pathway and could be meaningful for metastases formation." (PMID 38010391, 2023). "MUC1-C also induces the NOTCH1 stemness TF in promoting the NEPC cancer stem cell (CSC) state." (PMID 36835130, 2023). "Eight targets (EP300, CASP3, CASP8, CHEK2, CREBBP, NOTCH1, PPARG, and TGFBR2) were TSGs (gray text), suggesting that antagonizing these molecules might increase the susceptibility to cancer in healthy individuals." (PMID 37888486, 2023). "Significant differences in the mutation frequencies of NOTCH1 and NOTCH2 (more frequent in PNM than in ESCC); copy number variations at both the gene and chromosomal arm level; and mutations in cancer-related HIPPO, WNT and NRF2 signaling pathways (more frequent in ESCC than in PNM) were observed." (PMID 36661697, 2023). "In this way, MUC1-C activates the NOTCH1 gene and promotes the dedifferentiation of cancer cells." (PMID 37821650, 2023).
cancer (continued). "In KG-1α cells, overexpression of DLL1 could partially reverse the biological effect caused by knockdown of MSI2 through restoring the expression levels of the key factors of Notch1 signaling pathway and cancer stemness-related proteins." (PMID 37149661, 2023). "NOTCH1 signaling has been found to regulate chemoresistance in various cancers." (PMID 37373457, 2023). "In our sample of 22 patients, 15 with low-grade dysplasia, 2 with high-grade dysplasia, and 5 with carcinoma, the NOTCH1 mutation is not detected, so the sample studied does not present the mutation or is below the limits of software detection." (PMID 37008245, 2023). "All these factors can contribute to the migratory behavior in a context specific manner, and the interrelated roles of Nrf2 on EMT and Notch1 may explain the discrepancy on the functions of Nrf2 on the collective cancer migration." (PMID 35480877, 2022). "Finally, by comparing our results with known NOTCH1 alterations in cancers from which our mutations originated, we were able to establish a correlation between our results and the known GOF or LOF of NOTCH1 in these cancers." (PMID 36265581, 2022). "For example, overexpressed miR-122 has been reported to reduce Hes1 and NOTCH1 in A549 stem cells, and by blocking the NOTCH1 pathway, miR-122 can reduce the resistance of A549 stem cells to gefitinib, and thereby suppressing cancer cell proliferation and migration." (PMID 35123522, 2022). "Our findings not only unravel strategies in the amelioration of pathological retinal neovascularization but also have its relevance for translational vascular biology, as growing evidence suggests the role for Notch1 signaling in cancer progression and metabolic diseases." (PMID 35589941, 2022). "When the SCLC dataset was assessed, RB1 (73%) and NOTCH1 (13%) were the most altered cancer genes." (PMID 35330454, 2022). "Notably, among the genes downregulated upon DSCAM-AS1 knockdown were several proliferation activators of endometrial (and other) cancer cells, like NOTCH1, HMGA2, PTK2/FAK, FOSL1, GREM1 and EGR1." (PMID 35885035, 2022). "Cancer cells are known to induce an “activated” state in fibroblasts, either by secretion of various growth factors and cytokines or via direct cell-cell contact mediated by Notch1." (PMID 36618350, 2022). "In addition, I-BET151 impeded BRD4 binding to the NOTCH1 promoter, diminishing the expression of Hes1 and cancer-cell renewal activity." (PMID 35215234, 2022). "In addition, Notch1/MenaINV initiate invadopodium formation in cancer cells in a macrophage-dependent manner." (PMID 35385679, 2022). "Both JAG1 and NOTCH1 silencing decreased in vitro cancer spheroid formation." (PMID 35249111, 2022). "Notably, M2 macrophage infiltration as well as high NOTCH1 signaling in cancer cells indicated more aggressive features and worse survival in PCa patients." (PMID 36439868, 2022). "Notch 1 signaling directly activates the cyclooxygenase-2 (COX-2)/Snail/E-cadherin pathway, which subsequently induces cancerous cell invasion and migration; however, silymarin’s ability to down-regulate Notch1 prevents this cellular invasion and results in decreased cancer growth." (PMID 36014565, 2022). "In addition, in supratentorial (ST) EPN, NOTCH1 expression was associated with cancer stem cell (CSC) markers, VEGFA and L1CAM, and the ST_EPN_RELA subtype showed the activation of selected key members of the Notch signaling pathway (NOTCH1, JAG1, JAG2, HES4)." (PMID 36293188, 2022). "Inhibition of Notch-1 would result in down regulation of NF-κB, leading to cancer suppression." (PMID 35744941, 2022). "Besides, the activation of Notch1 signaling, which is induced by low expression of Smarcd1, is capable to maintain cancer cell stemness." (PMID 33190170, 2021). "Accordingly, Notch1 suppression is a potential strategy for cancer therapy." (PMID 34922602, 2021).